INHBC (inhibin subunit beta C)
Description:
Inhibins and activins inhibit and activate, respectively, the secretion of follitropin by the pituitary gland. Inhibins/activins are involved in regulating a number of diverse functions such as hypothalamic and pituitary hormone secretion, gonadal hormone secretion, germ cell development and maturation, erythroid differentiation, insulin secretion, nerve cell survival, embryonic axial development or bone growth, depending on their subunit composition. Inhibins appear to oppose the functions of activins.
Synonyms: IHBC
Tractability: Antibody: its Gene Ontology location is reachable by antibodies, with high confidence; UniProt places it where antibodies can reach, with medium confidence; UniProt predicts a signal peptide or a membrane-spanning region. PROTAC: its protein half-life has been measured.
Gene: Protein-coding gene on chromosome 12 (57,434,784 to 57,452,062, forward strand). Ensembl gene ENSG00000175189.
Subcellular location: Secreted
Subcellular location (Human Protein Atlas): Cytosol; Predicted to be secreted
Pathways (Reactome):
Metabolism of proteins: Glycoprotein hormones
Gene Ontology:
Molecular function: cytokine activity; transforming growth factor beta receptor binding; growth factor activity; hormone activity
Biological process: cell surface receptor protein serine/threonine kinase signaling pathway
Cellular component: extracellular region
Genetic constraint (gnomAD): Loss-of-function variants: 17 observed, 21.69 expected, observed/expected ratio (o/e) 0.78, 90% interval 0.54 to 1.18. The upper end of that interval is the gene's LOEUF score, 1.18, which puts it in group 5 of 6, group 1 being the genes least tolerant of losing a copy. Missense variants: 382 observed, 454.86 expected, observed/expected ratio (o/e) 0.84, 90% interval 0.77 to 0.91. Synonymous variants: 147 observed, 178.42 expected, observed/expected ratio (o/e) 0.82, 90% interval 0.72 to 0.94.
Homologues: Orthologues: chimpanzee INHBC (99% identical), pig INHBC (86% identical), dog INHBC (82% identical), rabbit INHBC (81% identical), guinea pig INHBC (80% identical), mouse Inhbc (76% identical), rat Inhbc (76% identical), tropical clawed frog inhbc.2 (39% identical). Paralogues in human: INHBE (40% identical), INHBB (38% identical), INHBA (36% identical), GDF11 (24% identical), BMP8B (22% identical), BMP6 (22% identical), BMP8A (22% identical), BMP10 (21% identical), MSTN (21% identical), BMP2 (20% identical), GDF2 (20% identical), GDF7 (20% identical), and 19 more.
Diseases named in the same sentence as INHBC in open-access papers:
INHBC is named in the same sentence as 16 diseases in open-access papers, as found by Europe PMC text mining. Sharing a sentence is not in itself a finding about the gene and the disease. The quoted sentences say what the papers report.
gout (4 papers, 2012 to 2023). A condition characterized by painful swelling of the joints, which is caused by deposition of urate crystals. "In contrast, rs3741414 (C > T) within INHBC was associated with lower SU concentrations in individuals of European ancestry (Effect size = −0.072, p = 2.2 × 10−25) and decreased risk for gout (OR = 0.87, p = 2.7 × 10−4)." (PMID 33810064, 2021). "Though the exact biological mechanism underlying the association of the forementioned SNPs and the risk of HU or gout is inconclusive, it is presumed that these genetic polymorphisms may reduce the repressor activity functions of RREB1 and INHBC." (PMID 33810064, 2021).
diabetic nephropathy (2 papers, 2021 to 2023). "For example, while INHBC was known to be genetically associated with eGFRcr and upregulated in patients with diabetic nephropathy, the neighboring association of SPRYD4 was less well studied, with only one study finding higher expression in kidney tissue." (PMID 37365616, 2023). "Higher INHBB was found in a polycystic kidney disease mouse model compared to controls, and higher INHBC expression was found in a diabetic nephropathy rat model." (PMID 37365616, 2023). "INHBC may also induce the secretion of IL-6 and TGF-β and promote the proliferation and inhibit the apoptosis of renal cells during diabetic nephropathy." (PMID 34641864, 2021).
ovarian carcinoma (2 papers, 2011 to 2012). A malignant neoplasm originating from the surface ovarian epithelium. "The initial split was defined by INHBC: rs2228225, indicating that this SNP is the primary factor contributing to variations in ovarian cancer risk in the study population." (PMID 21984931, 2011). "A recent study showed polymorphisms in INHBC is associated with ovarian cancer risk." (PMID 23284751, 2012).
prostate carcinoma (2 papers, 2022 to 2024). A carcinoma that arises from epithelial cells of the prostate gland. "INHBC is considered an oncogene in prostate cancer due to its effects when overexpressed." (PMID 37981656, 2024). "These stocks are valuable for testing new mechanistic hypotheses for INHBB and INHBC reported as a tumor suppressor or an oncogene in prostate cancer, respectively." (PMID 37981656, 2024).
asthma (1 paper, 2024). "Proteins TCN2,TNFRSF1B and C10orf54 were positively associated with the development of asthma (B>0); proteins PDGFD,INHBC and ANXA7 were negatively associated with the development of asthma (B<0)." (PMID 39318474, 2024).
Insulin resistance (1 paper, 2025). Increased resistance towards insulin, that is, diminished effectiveness of insulin in reducing blood glucose levels. "These unadjusted associations identified species that have been associated with insulin resistance and obesity for the protein (eg, CES1, INHBC, RTN4R), metabolite (α-aminoadipate, butyryl carnitine, tyrosine), and lipid (TG and DG species) assays." (PMID 39657693, 2025).
ovarian tumors (1 paper, 2022). "However, inhibin-α knock-out mice that have increased INHBA and develop testicular and ovarian tumors, were shown to have reduced tumor formation when modified to overexpress INHBC." (PMID 36612143, 2022).
prostate tumours (1 paper, 2022). "The findings from Oncomine and FireBrowse analysis of RNA expression are consistent with our protein expression results showing INHBB expression is higher, and INHBC is lower, in prostate tumours when compared to healthy prostate." (PMID 36612143, 2022).
tumor (5 papers, 2012 to 2024). "In contrast, the FireBrowse INHBC analysis showed a 0.388-fold decrease in INHBC expression in tumour samples compared to normal prostate samples." (PMID 36612143, 2022). "In contrast INHBC protein expression decreased in higher-grade tumors and RNA expression appeared lower in tumor samples compared to normal prostate tissue in a relatively large data set of RNAseq data from the TCGA." (PMID 36612143, 2022). "In the tumor-to-tumor signaling direction, activin receptor type-2B (ACVR2B) was implicated in three of the fifteen top-scoring interactions with corresponding ligands of bone morphogenetic protein 5 (BMP5), growth differentiation factor 11 (GDF11), and inhibin beta C chain (INHBC)." (PMID 36676129, 2023). "To evaluate the clinical significance of inhibin beta family genes (INHBA, INHBB, INHBC, and INHBE) in STAD, we investigated their interrelations and compared their expression levels between tumor and normal tissues." (PMID 39543755, 2024). "oe-lnc-SNHG10 exo induced tumor growth and upregulated INHBC expression in mice and downregulated the expression of perforin, granzyme B, and NK1.1 in tumor tissues." (PMID 34641864, 2021). "The opposing effects of overexpression of INHBB and INHBC on the immortalized epithelial PNT1A cells and metastatic PCa PC3 cells indicates a switch in the function of these activins from inhibiting or regulating growth in normal epithelial cells to being pro-oncogenic in tumor cells." (PMID 36612143, 2022).
cancer (4 papers, 2019 to 2024). A tumor composed of atypical neoplastic, often pleomorphic cells that invade other tissues. "INHBC and BMP2 are identified as the growth signals specifically needed by the cancer type, and f2x and f3x are their age-dependent distributions, respectively." (PMID 39796131, 2024).
INHBC also shares sentences with these, for which no sentence is quoted: brain disorder (1 paper); colorectal cancer (1); Hypertension (1); Kidney Disease (1); Obesity (1); polycystic kidney disease (1).